CDKN2C (cyclin dependent kinase inhibitor 2C)
Diseases named in the same sentence as CDKN2C in open-access papers (continued):
Sharing a sentence is not in itself a finding about the gene and the disease.
hepatocellular carcinoma (3 papers, 2020 to 2024). A malignant tumor that arises from hepatocytes. "For instance, overexpression of miR‐95‐3p promotes cell‐cycle G1/S transition by directly targeting p21, a CDKI encoded by CDKN2C in hepatocellular carcinoma." (PMID 32090490, 2020). "Here we find that CDKN2C overexpression in HBV-infected hepatocytes enhances replication in both NTCP-overexpressing hepatoma-derived cell line and in PHHs." (PMID 32483149, 2020).
brain tumor (2 papers, 2007 to 2013). "Candidate chromosome 1p brain tumor suppressor genes proposed so far, TP73, RAD54, CDKN2C/p18INK4c and CHD5, are located on distal 1p." (PMID 17593975, 2007).
breast invasive carcinoma (2 papers, 2008 to 2022). "Furthermore, the first pan-cancer analysis revealed the differential expression of CDKN2C in 16 cancers (breast invasive carcinoma, etc." (PMID 35751045, 2022). "Six cancers had downregulated CDKN2C expressions, namely breast invasive carcinoma (BRCA), colon adenocarcinoma (COAD), kidney chromophobe (KICH), prostate adenocarcinoma (PRAD), rectum adenocarcinoma (READ), and uterine corpus endometrial carcinoma (UCEC) (p < 0.05)." (PMID 35751045, 2022).
Hypercalcemia (2 papers, 2017 to 2023). An abnormally increased calcium concentration in the blood. "Familial segregation analysis of these variants identified the same variant of the CDKN2C gene in ID27’s mother, who was diagnosed with PHPT with moderate hypercalcemia and osteoporosis due to parathyroid adenoma." (PMID 37810884, 2023).
liver cancer (2 papers, 2019 to 2021). An epithelial or non-epithelial malignant neoplasm that arises from the liver. "Previous studies illustrated that HBx-mediated HULC upregulation promotes the increase of mRNA and protein levels in liver cancer by downregulating the tumor suppressor gene CDKN2C (p18)." (PMID 31341758, 2019). "In HCC, the lncRNA HULC (highly upregulated in liver cancer) sequesters miR-372, which represses the protein kinase PRKACB, and downregulates the tumor suppressor gene CDKN2C (p18)." (PMID 34002693, 2021).
liver disease (2 papers, 2020 to 2026). "Taken together, our data suggest that HBV infection modulates CDKN2C expression and that CDKN2C expression is associated with liver disease progression and poor survival." (PMID 32483149, 2020). "CDKN2C expression correlates with disease progression suggesting a potential role in HBV-induced liver disease." (PMID 32483149, 2020). "In fact, CDKN2C is an etiology-independent marker of liver disease and part of a regulatory signature involved in liver regeneration." (PMID 32483149, 2020). "To evaluate whether CDKN2C expression is associated with the development of virus-induced liver disease, we analyzed CDKN2C expression in HBV patients with advanced liver disease and HCC." (PMID 32483149, 2020). "A correlation between CDKN2C expression and disease progression in HBV-infected patients suggests a role in HBV-induced liver disease." (PMID 32483149, 2020).
male infertility (2 papers, 2022 to 2024). The inability of the male to effect fertilization of an ovum after a specified period of unprotected intercourse. "CDKN2C is differentially expressed in the testis of male infertility in cattleyak and is involved in testis development and spermatogenesis in mice." (PMID 39273345, 2024).
medullary thyroid carcinoma (2 papers, 2020 to 2024). "Similarly, cell‐cycle inhibitor CDKN2C has been reported to decrease cell proliferation in medullary thyroid carcinoma and nasopharyngeal cancer." (PMID 32090490, 2020).
neuroblastoma (2 papers, 2022). Neuroblastoma (NB) is the most common solid, extracranial childhood tumor. "These included the top MYCNARB1PRO downregulated TSTD1 and CDKN2C genes, which also showed a significantly lowered expression in MYCN-amplified compared with the MYCN-silent neuroblastomas." (PMID 36245757, 2022). "The analysis of MYCN-amplified versus MYCN-silent neuroblastoma also showed a significant downregulation of CDKN2C in MYCN-amplified samples, suggesting a potential, general oncogenic function for the lowered expression of CDKN2C for MYCN-amplified pediatric cancers." (PMID 36245757, 2022).
osteosarcoma (2 papers, 2016 to 2023). A usually aggressive malignant bone-forming mesenchymal neoplasm, predominantly affecting adolescents and young adults. "Experiments supported E2F-Sp1 interactions near: dihydrofolate reductase in Chinese hamster, dihydrofolate reductase in human osteosarcoma, fibroblast CTP:phosphocholine cytidylyltransferase in mouse embryo, thymidine kinase in mouse, RIP140 in human, CDKN2A, HMGA1, MYCN, and CDKN2C." (PMID 27871221, 2016).
ovarian carcinoma (2 papers, 2021 to 2025). A malignant neoplasm originating from the surface ovarian epithelium. "For instance, in BRCA1-mut ovarian cancer, KTR14, KRT16, CXCL9, and CFD were highly upregulated (more than 4-fold change), and in BRCA2-mut ovarian cancers, TSPAN7 and CDKN2C were clearly upregulated (more than 2-fold change)." (PMID 40647506, 2025).
prostate adenocarcinoma (2 papers, 2022). "However, there was a weak negative correlation for TNRC6C in TGCT; TFDP1 in LAML; CDKN2C in prostate adenocarcinoma (PRAD); and CDKN2A in KIRC and THCA." (PMID 35911954, 2022).
small cell lung carcinoma (2 papers, 2022 to 2025). Small cell lung cancer (SCLC) is a highly aggressive malignant neoplasm, accounting for 10-15% of lung cancer cases, characterized byrapid growth, and early metastasis. "Paradoxically, CDKN2C is overexpressed in certain cancer types, such as small-cell lung cancer, where elevated levels are associated with poor survival." (PMID 41226058, 2025). "Cyclin-dependent kinase inhibitor 2C (CDKN2C) was identified to participate in the occurrence and development of multiple cancers; however, its roles in small cell lung carcinoma (SCLC) remain unclear." (PMID 35751045, 2022).
acromegaly (1 paper, 2020). Acromegaly is an acquired disorder related to excessive production of growth hormone (GH) and characterized by progressive somatic disfigurement (mainly involving the face and extremities) and systemic manifestations. "Sixteen patients with acromegaly and PHP underwent rigorous genetic testing with DNA sequence analysis performed for genes including: MEN1, CDC73, CDKN1A, CDKN1B, CDKN2B, CDKN2C, and AIP, as well as MLPA to search for deletions or duplications in MEN1, CDC73, CDKN1B, and AIP genes." (PMID 32311048, 2020).
cervical squamous cell carcinoma (1 paper, 2022). A squamous cell carcinoma arising from the cervical epithelium. "Differentially expressed CDKN2C was also detected in 13 cancer cell lines, namely CESC (cervical squamous cell carcinoma and endocervical adenocarcinoma), CHOL, COAD, ESCA, HNSCC, KIRC, LIHC, pancreatic adenocarcinoma, PRAD, SCLC, STAD, THCA, and UCS (uterine carcinosarcoma)." (PMID 35751045, 2022).
colitis (1 paper, 2022). Inflammation of the colon. "Genes related to promoters differentially methylated uniquely in Dnmt3aΔIEC mice (e.g., Cdkn2c, Ccn5, Ctnnbip1, and Sfrp5) at day 5 after the initiation of DSS colitis were enriched in processes related to cell junction and cell proliferation." (PMID 36271073, 2022).
colon cancer (1 paper, 2022). "Additionally, this gene is a positive regulator of Wnt signaling, regulates the MYC oncogene, represses the cell cycle inhibitors CDKN2C/CDKN2D, and is a transcriptional driver of various oncogenes, contributing to the progression of colon cancer and other cancer types." (PMID 35992833, 2022).
diabetes mellitus (1 paper, 2024). A metabolic disorder characterized by abnormally high blood sugar levels due to diminished production of insulin or insulin resistance/desensitization. "Another study uncovered that iMSC-EVs transferred miR-21-5p and miR-486-5p to promote hippocampal neural stem cells (H-NSCs) proliferation and neurogenesis through inhibiting EphA4, CDKN2C, and FoxO1 expression in diabetes mellitus-postoperative cognitive dysfunction (DM-POCD)." (PMID 39135947, 2024).
familial isolated hyperparathyroidism (1 paper, 2023). A rare, autosomal dominant hereditary syndrome characterized by hypercalcemia, abnormally high levels of parathyroid hormone, and isolated hyperfunctioning parathyroid tumors. "Non-syndromic hereditary hyperparathyroidism, called familial isolated hyperparathyroidism (FIHP), can be caused by the incomplete manifestation of mutations of syndrome-related genes such as MEN-1, CDC73, GCM2, CDKN1A, CDKN1B, or CDKN2C." (PMID 36900197, 2023).
fibrosis (1 paper, 2020). the formation of excess fibrous connective tissue in an organ or tissue in a reparative or reactive process. "We first observed that patients with advanced fibrosis (F3) exhibit higher CDKN2C mRNA levels compared to patients with F1 or F2 fibrosis CDKNC2 expression." (PMID 32483149, 2020).
glaucoma (1 paper, 2023). Increased pressure in the eyeball due to obstruction of the outflow of aqueous humor. "On the other hand, Cdkn2c (cyclin-dependent kinase inhibitor 2c) was upregulated in the UON at the three day crush time point, and Cdkn3 (cyclin-dependent kinase inhibitor 3), which prevents the activation of Cdk2, was also increased in early glaucoma in this same region." (PMID 37762022, 2023).
glomerulonephritis (1 paper, 2022). A renal disorder characterized by damage in the glomeruli. "It has been found that the gene Cdkn2c, a gene encoding for cyclin-dependent kinase inhibitor p18Ink4c, which can regulate the cell cycle to control B-cell multiplication, is associated with the expansion of B1 cells and the development of glomerulonephritis." (PMID 35418972, 2022).
hearing loss (1 paper, 2025). "This identifies Cdkn2c and its regulatory pathway as potential therapeutic targets for hearing loss associated with hair cell depletion." (PMID 41257804, 2025).
Infertility (1 paper, 2022). "Furthermore, the Wilcox test revealed a significant association of RPS9, DUT, CDKN2C and MARF1 genes with infertility in the red, blue, and turquoise modules." (PMID 35603216, 2022).
lung adenocarcinoma (1 paper, 2024). A carcinoma that arises from the lung and is characterized by the presence of malignant glandular epithelial cells. "Furthermore, CBX8-PRC1 promotes lung adenocarcinoma growth and metastasis through transcriptional repression of CDKN2C and SCEL." (PMID 38816356, 2024).
Merkel cell carcinomas (1 paper, 2016). "The cell cycle pathway (CDKN2A/B, CDKN2C or RB1 genes) was also abnormal in 71% of patients (12/17) with Merkel cell carcinomas." (PMID 26981779, 2016).
multiple endocrine neoplasia (1 paper, 2025). Multiple endocrine neoplasia (MEN) is a group of rare inherited cancer syndromes characterized by the development of two or more endocrine gland tumors, sometimes with tumor development in other tissues or organs. "These abnormalities are often linked to syndromes such as Multiple Endocrine Neoplasia (MEN-1, MEN-2A, MEN-4) or mutations in genes such as CASR, CDKN1A, CDKN1B, CDKN2C, and RET." (PMID 41597072, 2025).
pancreatic cancer (1 paper, 2014). "Significantly, cancer gene AKT2 was amplified in two pancreatic cancer patients, and cancer gene CDKN2C was homozygously deleted in other two cases." (PMID 25502777, 2014). "However, there was still little information about the role of CDKN2C in pancreatic cancer." (PMID 25502777, 2014).
prostatic intraepithelial neoplasia (1 paper, 2022). "CDKN2C is upregulated during the transition from prostatic intraepithelial neoplasia to PCa, which may be associated with cell adhesion and invasion of PCa cells." (PMID 36471446, 2022).
renal carcinoma (1 paper, 2022). A carcinoma arising from the epithelium of the renal parenchyma or the renal pelvis. "For example, for renal cancers, upregulated CDKN2C expression was detected in KIRC, while the downregulated expression of CDKN2C was identified in the other subtype of renal cancer—KICH." (PMID 35751045, 2022).
retinoblastoma (1 paper, 2022). A malignant tumor that originates in the nuclear layer of the retina. "TSTD1, CDKN2C, NUCB2, and KATNAL1 showed the most significant MYCNARB1PRO-specific downregulated expression pattern among the hypermethylated genes in this retinoblastoma subtype." (PMID 36245757, 2022).
teratoma (1 paper, 2022). A non-seminomatous germ cell tumor characterized by the presence of various tissues which correspond to the different germinal layers (endoderm, mesoderm, and ectoderm). "In human teratoma and thyroid tumor, mutant CDKN2C has been proven to predict poor prognosis." (PMID 36017503, 2022).
tumor (60 papers, 2006 to 2025). "One tumor sample, PD47450e, harbored a truncating mutation in CDKN2C, which in addition to the loss of the short arm of chromosome 1 would have resulted in biallelic knockout of this important regulator of cell cycle progression." (PMID 36345344, 2022). "E7 tumour has the highest expression of CDK6 associated with high levels of CDKN2C." (PMID 36453028, 2024). "Conversely, in case 3, genetic tumour testing showed uniparental disomy of chromosome 1, including CDKN2C gene, which could support a pathogenic role of this variant." (PMID 36334246, 2023). "One copy loss of CDKN2C was also detected in one localized tumor." (PMID 26544626, 2015). "Co-occurring CN loss and hypomethylation events were more prevalent in LUSC, affecting TSGs including NCOR1 (29 of 59 tumor regions), CDKN2C (28 of 59 tumor regions), CREBBP (26 of 59 tumor regions) and RPL22 (9 of 59 tumor regions)." (PMID 40931149, 2025). "Stiff 3D culture wasassociated with the downregulation of tumor suppressors (LATS1, BCAR3, CDKN2C), as well as theupregulation of cancer-associated genes (RAC3)." (PMID 38466617, 2024). "Genetic analysis of tumour samples showed uniparental disomy of chromosome 1, including CDKN2C, in case ID27." (PMID 37810884, 2023). "The deleted regions contained the tumour suppressors CDKN2C, SDHB, and SFPQ in 1p and CDKN2A in 9p in metastatic samples and the tumour suppressors BCL10 and NOTCH2 and the oncogenes JAK1 and NRAS in 1p in the non‐metastatic sample group." (PMID 37622176, 2023). "The patient we presented was initially diagnosed with IgD-λ RRMM, accompanied by rare complex karyotypes, CKS1B (1q21) and CDKN2C (1p32.3) genetic abnormalities, and high tumor burden." (PMID 34003300, 2022). "CDKN2C (cyclin-dependent kinase inhibitor 2C), also known as p18INK4C, is considered a tumor-suppressor gene." (PMID 36017503, 2022). "In patients, CDKN2C expression is accompanied with progression of HBV-associated fibrosis and is higher in HBV-associated cirrhotic and HCC tissues compared to tumor-adjacent tissues." (PMID 32483149, 2020). "Conversely, loss of the endogenous CDK4/6 inhibitors (CDKN2A, CDKN2B, CDKN2C, and CDKN2D) or RB-family (RB1, RBL2, and RBL1) are also observed in specific tumor settings, in total the RB-pathway is subject to genetic perturbation in greater than 30% of tumors." (PMID 32242058, 2020). "In contrast, the switches in the tumor drivers CDKN2C and CTNNB1, the former in LUSC and LUAD and the latter in LUSC, do not affect the protein." (PMID 25578962, 2015). "Interestingly, genes with oncogenic potential, including CDC42, CDC14B, STK40, BRD3, CPNE1, and MCM3, were downregulated, whereas tumor inhibitors, including CDKN2C, CASP7, and CDKN1B, were upregulated by RBM15 depletion." (PMID 38825643, 2024).